BACE1 (beta-secretase 1)
Diseases named in the same sentence as BACE1 in open-access papers (continued):
Sharing a sentence is not in itself a finding about the gene and the disease.
neuroblastoma (continued). "Higher β-secretase-mediated APP processing, suggested by a greater ratio of β-CTF: full-length APP, corresponded with an increase in BACE1 protein expression in human neuroblastoma cells." (PMID 28187176, 2017). "For instance, we have shown that HIF1α binding to the BACE1 promoter induces BACE1 expression and results in increased Aβ production in neuroblastoma cells." (PMID 28790888, 2017). "The impact APP processing in this subcellular localization was assessed by the overexpression of APP or BACE1 in human HEK293 cells (expressing low endogenous BACE1 expression) and N2a murine neuroblastoma cell line." (PMID 29204109, 2017). "Altogether, this set of data indicates that XBP-1s down-regulates BACE1 at a post-transcriptional level in both human neuroblastoma cells and mouse fibroblasts." (PMID 27853315, 2016). "In a separate investigation, the addition of hydrogen peroxide in human neuroblastoma cells resulted in enhanced expression of BACE1, supporting the observation that OS can heighten BACE1 levels." (PMID 26543520, 2015). "Further, endogenous expression of BACE1 protein was also reduced by CHIP in human neuroblastoma cells (SH-SY5Y)." (PMID 25773675, 2015). "In a subsequent step, BACE1 and γ-secretase activities were quantified in differentiated SK-N-BE neuroblastoma cells challenged with a single dose of either 27-OH or 24-OH (1 μm)." (PMID 24612036, 2014). "Increased levels of activated caspase-3 were also shown to accompany the increase in BACE1 expression observed in differentiated human NT2 neuroblastoma cells undergoing 4-hydroxynonenal-mediated oxidative stress." (PMID 23613819, 2013). "Hypoxia or overexpression of HIF-1α increases the BACE1 mRNA and protein levels in mouse neuroblastoma N2a cells." (PMID 21541279, 2011). "Using SH-SY5Y human neuroblastoma cells, we determined the effects of clinically relevant concentrations of three BACE-1 inhibitors (elenbecestat, lanabecestat and verubecestat) and two non-BACE-1 anti-AD drugs (memantine and galanthamine) on endolysosome and mitochondrial stress responses." (PMID 40313365, 2025). "Furthermore, enhanced BACE1-mediated processing of APP corresponded with an increase in BACE1 expression in human neuroblastoma cells." (PMID 40722590, 2025). "To investigate how pharmacological inhibition can affect endogenous BACE1 amyloidogenic and amyloidolytic activities in wild-type human neuroblastoma SH-SY5Y cells, we measured AD-related protein levels in the absence or presence of the BACE1-selective inhibitor VBA2092464 (termed “R3”)." (PMID 38944120, 2024). "Moreover, NMN lowered the protein levels of 6E10 (full-length APP, C99), BACE-1, and CTFs in mouse neuroblastoma N2s cells, suggesting a possibility of amelioration in Aβ pathology of NMN by inhibition of BACE-1 activity." (PMID 39394148, 2024). "MiR-384 can downregulate BACE1 expression in human neuroblastoma cells as well." (PMID 38003448, 2023). "MiR-340 can downregulate BACE1 expression in human neuroblastoma cells." (PMID 38003448, 2023). "MiR-16-5p and miR-19b-3p can reduce BACE1 protein levels in human neuroblastoma cells." (PMID 38003448, 2023). "Moreover, miR-29a and miR-29b-1 can downregulate BACE1 expression in human neuroblastoma cells, and these miRNAs were found to be downregulated in a cohort of AD patients with aberrantly high BACE1 levels." (PMID 38003448, 2023). "In addition, nano-emulsions of naringenin downregulated APP and β-secretase (BACE1) expression in Aβ-induced neurotoxicity in a human neuroblastoma cell line (SH-SY5Y)." (PMID 38204816, 2023). "To further determine whether PGRN could inhibit BACE1 expression, we treated N2a cells, a mouse neuroblastoma cell line with high BACE1 expression, with various concentrations of PGRN in vitro." (PMID 32973454, 2020).
neuroblastoma (continued). "The molecular mechanism of the observed capsaicin induced elevated β-secretase cleavage of APP was further examined in neuroblastoma cells by analyzing BACE1 protein levels, gene expression and by performing β-secretase assays in living cells and purified membranes." (PMID 32514053, 2020). "- Regulates BACE1 mRNA expression in SY5Y neuroblastoma cells." (PMID 30405389, 2018). "Hence, ANG-SI is efficiently internalized by neuroblastoma cells, where it accumulates inside endosomal vesicles together with the target enzyme BACE1." (PMID 27682851, 2016). "Also hypoxia-induced oxidative stress was reported to elevate BACE1 proteins in viable differentiated SK-N-BE neuroblastoma cells." (PMID 23613819, 2013). "Human neuroblastoma cells were treated with increased concentration of oligomeric Aβ1-42 for 24 h in order to study their neurotoxic abilities and to find the range of concentrations that do not produce a significant cytotoxicity to carry out the experiments on BACE1 regulation." (PMID 33014268, 2020). "To investigate the effects of ramalin on regulating BACE1 expression, we treated both SH‐SY5Y neuroblastoma cells and mouse primary cortical neurons with increasing concentrations of ramalin." (PMID 41488470, 2026). "BACE1 and TAU were identified as new direct targets for miR-455-3p, with overexpression of miR-455-3p leading to a reduction in the expression of APP, BACE1 and TAU in neuroblastoma cells." (PMID 35008980, 2022). "Reducing folate and vitamin B12 uptake in neuroblastoma cell lines diminishes SAM levels and reduces methylation in promoter regions of beta-site amyloid precursor protein cleaving enzyme 1 (BACE1) and presenilin 1 (PSEN1) genes." (PMID 35053330, 2022). "Expression of APP, BACE1 and TAU were all decreased after overexpression of miR-455-3p in SH SY5Y neuroblastoma cells." (PMID 35008980, 2022). "To investigate the relationship between APP O-GlcNAcylation and APP endocytosis, we tested the effects of insulin on neuroblastoma SH-SY5Y cells overexpressing APP and BACE1, and cultured rat hippocampal neurons." (PMID 34940409, 2021). "We used human neuroblastoma SH-SY5Y cells stably transfected with APP751 and BACE1 (SH-SY5Y-APP/BACE1)." (PMID 33255194, 2020). "To address the role of Aβ and oxidative stress in the regulation of BACE1 expression, we have analyzed the effect of subtoxic concentrations of Aβ oligomers (0.25 μM) and H2O2 (10 mM) on a human neuroblastoma cell line." (PMID 33014268, 2020). "For example, the inflammatory cytokine IL-8 has been shown to increase beta-secretase 1 (BACE-1), amyloid precursor protein (APP) processing and Aβ production in SH-SY5Y neuroblastoma cells." (PMID 27309956, 2016). "To compare APP- versus Aβ mediated mitochondrial toxicity in intact cells we performed an overexpression of APP or BACE1 in human embryonic kidney cells (HEK293) and in a murine neuroblastoma cell line (N2a)." (PMID 28005987, 2016). "In experiments where neuroblastoma cells were cultured under low folate and vitamin B12 conditions, PSEN1 and BACE1 were hypomethylated, mRNA expression of BACE1 and PSEN1 was significantly induced, and Aβ production was increased." (PMID 24877062, 2014). "This was corroborated by studies showing that treatment of differentiated neuroblastoma cell lines with H2O2 and 4-hydroxynonenal increased BACE1 protein and mRNA levels." (PMID 23613819, 2013). "We examined how IL-18 affects protein levels of particularly BACE-1 and PS-1 in neuron-like differentiated SH-SY5Y neuroblastoma." (PMID 22898493, 2012). "Under high-glucose condition, BACE1 is upregulated with increased Aβ production through HIF-1α activation and decreased LXRα expression via the JNK pathway in a ROS-dependent manner in SK-N-MC, a neuroblastoma cell line." (PMID 39594520, 2024).
neuroblastoma (continued). "The DEPMAP project CRISPR (DepMap Public 23Q2 + Score, Chronos, accessed on 30 October 2023) indicated that synovial sarcoma and neuroblastoma cell lines are dependent on BACE1 expression, whereas head and neck cancers are not." (PMID 38248330, 2024). "MiR-298 reduces APP and BACE1 in one type of human astrocytes U373 but not in human differentiated neuroblastoma or microglia cells." (PMID 35197498, 2022). "We co-transfected neuroblastoma N2a cells with APP:YFP and BACE1:CH." (PMID 35445022, 2022). "MiR-298 significantly reduced (~ 30%) APP and BACE1 mRNA levels in astrocytes (U373) but not in differentiated neuroblastoma cells (SK-N-SH)." (PMID 35197498, 2022). "Also decreased expression of BACE-1 and APP was demonstrated after caffeine treatment in human neuroblastoma SH-SY5Y cells exposed to AlCl3 and Aβ." (PMID 33562156, 2021). "In the current study, we showed that O-GlcNAcylated APP in response to insulin could reduce the localization of APP in lipid rafts using neuroblastoma SH-SY5Y cells expressing APP and BACE1 as well as cultured hippocampal neurons from Sprague Dawley rats." (PMID 34940409, 2021). "Interestingly, BACE1 and nicastrin (components of γ-secretase) levels increased in HSV-1 infected human neuroblastoma SHSY5Y cells; HSV-1 can also elevate IFN-induced PKR level, leading to the expression of BACE1, which is otherwise constitutively inhibited." (PMID 35008671, 2021). "Moreover, the glucocorticoid receptor (GR) mediated the effects of CORT on the stimulation of the expression of BACE-1 and PS1 via the PKA and CREB pathways in neuroblastoma N2a cells." (PMID 33519376, 2020). "The effect of IL-18 on human neuroblastoma cells (SH-SY5Y) has previously been reported, in which IL-18 significantly upregulated the expression of several AD-related genes such as PS1 and BACE1." (PMID 32033164, 2020). "Thus, we created stable murine neuroblastoma cells overexpressing myc-tagged APP (N2a APPmyc), HA-tagged BACE1 (N2a BACE-HA) or HA-tag alone (N2a HA)." (PMID 28005987, 2016). "In murine neuroblastoma cells Neuro2a overexpressing the mutant APPswe (N2a/APPswe), CUR treatment decreased the expression of presenilin-1 (PS1; γ-secretase) and beta-site amyloid precursor protein cleaving enzyme 1 (BACE-1; β-secretase), proteases involved in the synthesis of Aβ plaques." (PMID 27110749, 2016). "We therefore examined, using a human neuroblastoma (SH-SY5Y) cell line, whether increased BACE1 activity is responsible for a reduction in cellular glucose metabolism." (PMID 26483636, 2015). "BACE1 is mainly located in the distal Golgi membrane but not considerably present at the plasma membrane of neuroblastoma cells." (PMID 23902727, 2013). "In a follow-up study, we showed that elevated BACE1 activity increased release of Navβ2-ICD (intracellular domain) through cleavage of Navβ2 resulting in elevated protein and mRNA levels of Nav1.1 α subunits in neuroblastoma cells." (PMID 21182789, 2010). "Reciprocally, exogenous expression of PGC-1α in N2a neuroblastoma cells could regulate APP processing by downregulating the transcription of BACE1, which effected decreased secreted Aβ and increased non-amyloidogenic soluble APPα." (PMID 32471464, 2020). "Besides inhibiting the BACE-1 activity, fucofuroeckol-B exhibited neuroprotective effects against β-amyloid toxicity by reducing the BACE-1-catalyzed cleavage of APP and Aβ generation in a transgenic human neuroblastoma cell line (SH-SY5Y-APP695swe)." (PMID 33353007, 2020). "Moreover, HSV-1-induced PKR activation in neuroblastoma cells and peripheral nervous tissue from infected mice has been suggested to increase the amyloidogenic APP processing and Aβ production by promoting BACE1 translation via eIF2α phosphorylation." (PMID 22899188, 2012).
neuroblastoma (continued). "However, the reduction in BACE1 levels was only detected in homozygous but not in heterozygous Septin5 knockout mice or after the downregulation of SEPTIN5 in neuroblastoma or cultured primary mouse cortical cells, suggesting that a complete loss of Septin5 was needed for this effect." (PMID 33203136, 2020).
dementia (63 papers, 2013 to 2025). Loss of intellectual abilities interfering with an individual's social and occupational functions. "The impact of sexual dimorphism in BACE1 levels has been already documented in animal and human (including post-mortem) studies and has been linked to the greater risk of dementia in women compared to men." (PMID 39828771, 2025). "Reported activities include anti-cholinesterase, antioxidant, BACE1 inhibition, and anti-inflammatory activities, all of which have potential in the treatment of dementia associated with neurodegenerative diseases such as Alzheimer’s and Parkinson’s." (PMID 39996817, 2025). "Our results suggest that rare variants in the PLAU and BACE1 genes should be considered in future studies on early-onset dementias." (PMID 34828412, 2021). "After, we performed a deeper analysis of the association of BACE1 with GFAP around vessels in the CA1 area of the hippocampus in human brains with dementia." (PMID 34025357, 2021). "Genetic factors that increase Aβ aggregation cause AD and variants in BACE1 have also been associated with dementia in Down's syndrome." (PMID 26788404, 2015). "In this context, the determination of CRP could be used in the future as a component of risk calculations for the development of dementia, in addition to the quantification of NF-L and BACE1 as well as epigenetic and protein-based methods." (PMID 36358351, 2022). "Although BACE1 modulation in people with clinically diagnosed dementia appears to lack therapeutic efficacy, the targeting of this pathway in the elderly with cognitive decline or those at high risk of dementia remains an area of current interest." (PMID 30572184, 2019). "The current failure rate of finding BACE1 inhibitors has driven research interests towards the search for alternative small molecules with therapeutic potential for reducing risk or slowing progression of dementia associated with AD." (PMID 27754406, 2016). "Furthermore, certain studies have observed that patients in the late stages of dementia showed lower levels of BACE1, which may be attributed to brain atrophy and the loss of the synaptic sites." (PMID 40748886, 2025). "Therefore, revealing the underlying mechanism of BACE1 in the pathogenesis of AD might have a significant impact on the future development of therapeutic agents targeting dementia." (PMID 31223308, 2019). "Given the evidence that increased APP processing by Bace1 leads to human dementia and that β-CTF can have a pathogenic role, it will be important to understand whether full-length APP and β-CTF can differentially regulate pre-synaptic vesicles exocytosis, endocytosis and recycling." (PMID 25247712, 2014). "Further research is needed to ascertain the real impact of BACE1 in Aβ homeostasis and the reliability of sBACE1 as predictor of dementia in SCD individuals." (PMID 39828771, 2025). "Fourth, in a previous large study, we found that serum BACE1 activity was able to discriminate AD from a group defined as “other dementia”, including Lewy Body disease, Parkinson’s dementia, FTD, and similar diseases." (PMID 39125924, 2024). "These mice also exhibited dementia-like pathological characteristics in terms of elevated BACE1 and tau expression." (PMID 39224568, 2024). "BACE1 and SCD1 associations had a close relationship with cPLA2 and PHF-tau in the human brain with dementias (FAD, SAD, and CADASIL), mainly in FAD and SAD." (PMID 37744400, 2023). "In summary, BACE1 and SCD1 associations had a close relationship in neurodegeneration in in vitro and in vivo models and in human dementia brains." (PMID 37744400, 2023). "Among them, platelet tau, A-β-PP (especially coated platelets) and secreted ADAM-10 and BACE1 are the most promising for clinical diagnosis of dementia." (PMID 33824766, 2021). "In this research, our data support a generalized increase of BACE1 IR in the hippocampus of all dementia cases by immunohistochemistry." (PMID 34025357, 2021).
dementia (continued). "In subiculum we detected a significant increase of BACE1 in all dementia cases being significant in FAD and CADASIL respect to the control group." (PMID 34025357, 2021). "As confirmation of these results, multivariable logistic regression analysis showed that higher BACE1 activity (IV quartile) was associated with the diagnosis of LOAD, VAD, and MIXED dementia after adjustment for age and gender." (PMID 32917964, 2020). "Several APP mutations cause familial Alzheimer’s disease (AD), while the Icelandic APP mutation near the BACE1-cleavage site protects from sporadic dementia, emphasizing APP’s role in dementia pathogenesis." (PMID 32022689, 2020). "In conclusion, we showed for the first time that the increase in peripheral BACE1 activity is a common feature of LOAD and VAD, thus underlying a further pathogenic link between these two forms of dementia." (PMID 32917964, 2020). "The finding of elevated BACE1 biomarkers in individuals with MCI compared to ADD was discussed in relation to extensive dendritic remodeling and neuronal loss characterizing dementia stages." (PMID 33066807, 2020). "In this context, Rosen and colleagues found that BACE1 activity was significantly increased in AD patients with mild dementia compared to patients at more severe stages." (PMID 33066807, 2020). "As the second step, we evaluated the possible influence of potential confounding factors on the association between BACE1 activity and the diagnosis of LOAD, VAD, or MIXED dementia." (PMID 32917964, 2020). "In contrast, humans carrying the Icelandic APP variant, which codes for an APP protein that is inefficiently cleaved by BACE1, are protected from dementia and normal cognitive decline." (PMID 31496118, 2019). "Multiple clinical trials suggested that BACE-1 inhibitors attenuate Aβ accumulation but fail to improve dementia." (PMID 31086208, 2019). "On the contrary, miRNA-195-5p, elevated in AD and sCJD, downregulates Aβ production by targeting APP and BACE1, and protects against chronic brain hypoperfusion-mediated dementia." (PMID 29357384, 2018). "Recent findings suggest that products of BACE1-processing of APP (predominantly ß-CTF) trigger several pathological features related to human dementias both in a mouse model of FDD and human neurons derived from familial and sporadic AD." (PMID 23451158, 2013). "Similarly, its inhibition has been demonstrated to upregulate β-site amyloid precursor protein cleaving enzyme 1 (BACE1) in the hippocampus under CCH both in dementia patients and rat models, implying a regulatory role of miR-124." (PMID 39965251, 2025). "In addition, curcumin reduced Beta-site APP Cleaving Enzyme 1 (BACE1) expression, a key protease in Aβ generation in dementia, through the estrogen receptor β (ERβ) and NF-κB signaling pathway in SH-SY5Y cells." (PMID 41473190, 2025). "Several studies have observed elevated BACE1 serum levels in individuals with early-stage AD who exhibited a better cognitive function and subsequently progressed to dementia, indicating the potential of serum BACE1 levels as an early predictor of cognitive decline." (PMID 40748886, 2025). "Therefore, VIP maintained the intrinsic inhibitory activity of GSK3β and BACE1 and exerted a synergistic anti-dementia therapeutic effect, which was consistent with the improvement in behavioral tests observed in APP/PS1 mice treated with VIP@siScr." (PMID 38734698, 2024). "So, it needs to be studied whether ADT promotes BACE1 expression in the neurons, and, potentially, BACE1 inhibitor/s could be useful in preventing dementia development in PCa patients, along with reducing tumor burden." (PMID 38201438, 2023). "As increased BACE1 activity is connected to dementia, inhibiting or reducing BACE1 activity could aid AD therapy." (PMID 38304326, 2023). "In this last sense, it is widely known that BACE1 and PHF are upregulated in dementia and are highly associated upstream with the proinflammatory cascade surrounding the Aß hypothesis." (PMID 37744400, 2023).